STK3 (serine/threonine kinase 3)
Diseases named in the same sentence as STK3 in open-access papers (continued):
Sharing a sentence is not in itself a finding about the gene and the disease.
ovarian carcinoma (2 papers, 2020 to 2024). A malignant neoplasm originating from the surface ovarian epithelium. "Low STK3 expression was associated with a worse prognosis in ovarian cancer, and its restoration significantly inhibited cell proliferation, apoptosis, and migration in different cancers in vitro and suppressed tumour growth in vivo." (PMID 38215077, 2024). "In TCGA cohorts, which included 428 samples of ovarian cancer, the low STK3 expression was associated with poorer overall survival and progression-free survival prognosis (P value <0.05)." (PMID 33062724, 2020). "Genetic or epigenetic mechanisms (or both) might cause dysregulation of the STK3 expression in ovarian cancer." (PMID 33062724, 2020). "Bisulfite sequencing PCR analysis was performed to validate the methylation of STK3 in ovarian cancer." (PMID 33062724, 2020). "We determined the effect of STK3 on ovarian cancer cells apoptosis by annexin V/PI staining and flow cytometry analysis in vitro." (PMID 33062724, 2020). "The poor prognosis in ovarian cancer also correlated with the lower STK3 expression in GSE9899 (P value <0.05)." (PMID 33062724, 2020). "Serine/threonine protein kinase-3 (STK3) is a critical molecule of the Hippo pathway but little is known about its biological functions in the ovarian cancer development." (PMID 33062724, 2020). "To investigate the level of STK3 in ovarian cancers, we first compared the expression of STK3 in ovarian cancer and matching normal ovarian surface epithelial tissue samples via GTEx and TCGA." (PMID 33062724, 2020). "The STK3 expression levels detected by western blot were lower in most tested ovarian cancer cells compared with IOSE80." (PMID 33062724, 2020). "The overexpression of STK3 in ovarian cancer cells induced cell cycle arrest at G2/M and a higher rate of cell apoptosis." (PMID 33062724, 2020). "To determine the effect of STK3 on the migration and invasion in ovarian cancer cells, we first examined the migration of OVCAR3 and OVCAR8 cells via transwell invasion and migration assays after overexpressing STK3." (PMID 33062724, 2020). "In this study, bioinformatic analysis showed that STK3 has low levels in ovarian cancer tissues, and the reduced expression of STK3 is closely related to the poor prognosis of patients suffering ovarian cancer." (PMID 33062724, 2020). "We performed GO enrichment analysis and KEGG pathway enrichment analysis based on RNA-seq results of ovarian cancer cells in the control group and STK3 overexpression group." (PMID 33062724, 2020). "The results showed that, compared with the control group, the invasive and migratory abilities of ovarian cancer cells were significantly decreased after exposure to overexpressed STK3 (P value <0.05)." (PMID 33062724, 2020). "The phosphorylation level of p65 and NF-κB inhibitor alpha (IkBα) in ovarian cancer regulated by STK3 was also investigated." (PMID 33062724, 2020). "We determined the effect of STK3 on the proliferation of ovarian cancer cells through CCK-8 and colony formation assays." (PMID 33062724, 2020). "RNA sequencing and gene set enrichment analysis (GSEA) were used to compare the transcriptome changes in the STK3 overexpression ovarian cancer and control cells." (PMID 33062724, 2020). "To further explore the role of STK3 in ovarian cancer progression in vitro, we established stable STK3-overexpressing cells by lentivirus-mediated transfection." (PMID 33062724, 2020). "In this study, we demonstrated that STK3 was downregulated in ovarian cancer via epigenetic methylation of its promoter DNA." (PMID 33062724, 2020). "For example, hypermethylation of the promoter region of the STK3 gene contributes to the downregulation of the STK3 expression in soft tissue sarcoma, which is consistent with our result on ovarian cancer." (PMID 33062724, 2020). "The overexpression of STK3 significantly inhibited cell proliferation, apoptosis, and migration of ovarian cancer cells in vitro and tumor growth in vivo." (PMID 33062724, 2020).
ovarian carcinoma (continued). "This study showed that upregulated serine/threonine kinase STK3 inhibits ovarian cancer aggressiveness and is correlated with CD8+ T-cells chemotaxis." (PMID 33062724, 2020). "To study the possible mechanism of STK3 in ovarian cancer, we compared the transcriptome of STK3 overexpressed ovarian cancer OVCAR8 cells with that of control cells by high-throughput transcriptome sequencing (RNA-seq)." (PMID 33062724, 2020). "To validate the methylation-mediated downregulation of STK3 in ovarian cancer, we performed bisulfite sequencing PCR of DNA from IOSE80, CAOV3, OVCAR3, and OVCAR8 cells." (PMID 33062724, 2020). "The STK3 promoter in ovarian cancer cells showed significantly higher levels of methylation compared with that in IOSE80 (CAOV3: 43%; OVCAR3: 64%; and OVCAR8: 87%) (Figure 3cP value <0.05)." (PMID 33062724, 2020). "To study the expression pattern of STK3 in ovarian cancer, we compared the level of STK3 in a normal human ovarian surface epithelium cell line (IOSE80) with levels in ovarian cancer cell lines (CAOV3, OVCAR3, OVCAR8, and ES-2)." (PMID 33062724, 2020). "We used GSEA to analyze the differentiated genes in the high and low STK3 expression groups in the TCGA ovarian cancer database." (PMID 33062724, 2020). "We also investigated whether the STK3 expression was correlated with prognosis in ovarian cancer patients." (PMID 33062724, 2020). "The overexpression of STK3 can promote ovarian cancer cells to secrete CXCL16 and CX3CL1." (PMID 33062724, 2020). "We used flow cytometry to detect the effect of STK3 on the ovarian cancer cell cycle distribution." (PMID 33062724, 2020). "Similarly, in the present study, we found that the overexpression of STK3 inhibits the invasion, proliferation, and metastasis of ovarian cancer cells and promotes their apoptosis." (PMID 33062724, 2020). "STK3 inhibited proliferation and metastasis of ovarian cancer cells." (PMID 33062724, 2020). "We explored the epigenetic regulation of the STK3 expression in ovarian cancer." (PMID 33062724, 2020). "Using 5-aza-20-deoxycytidine (DAC), a specific methyltransferase inhibitor, and Trichostatin A (TSA), a histone deacetylase inhibitor, we found that the mRNA expression level of STK3 in ovarian cancer cells was significantly increased after DAC treatment (P value <0.05), but not by TSA treatment." (PMID 33062724, 2020). "Notably, STK3 was significantly downregulated in ovarian cancer based on the analysis of TCGA and GEO datasets (P value <0.05)." (PMID 33062724, 2020). "Our study further confirmed that STK3 may indirectly participate in suppressing ovarian cancer by regulating the activity of LATS1/2 and YAP." (PMID 33062724, 2020). "Besides STK3, other components of the Hippo pathway have roles in ovarian cancer." (PMID 33062724, 2020). "STK3 may regulate immune microenviroment of ovarian cancer cells by affecting NF-κB signaling." (PMID 33062724, 2020). "However, it is unclear whether STK3 can activate NF-κB signaling and suppress ovarian cancer growth." (PMID 33062724, 2020). "Thus, the overexpression of STK3 inhibited the invasion and migration of ovarian cancer cells." (PMID 33062724, 2020). "STK3 might exhibit a regulatory role on CD8+ T cell infiltration in ovarian cancer." (PMID 33062724, 2020). "We also found that STK3 promoted the recruitment of CD8+ T-cells via an increase in chemokine CXCL16 and CX3CL1 production in human ovarian cancer cells." (PMID 33062724, 2020). "Therefore, we believe that STK3 may be a good prognostic marker for ovarian cancer." (PMID 33062724, 2020). "The results showed that, compared with the control group, the proliferation and clone formation ability of ovarian cancer cells OVCAR3 and OVCAR8 were significantly inhibited by overexpressing STK3 (P value <0.05)." (PMID 33062724, 2020). "STK3 is located on chromosome 8q22.2, and there is no deletion in this region in ovarian cancer." (PMID 33062724, 2020).
soft tissue sarcoma (2 papers, 2017 to 2020). A malignant neoplasm arising from muscle tissue, adipose tissue, blood vessels, fibrous tissue, or other supportive tissues excluding the bones. "Also, hyper-methylation of STK3 has been found in soft tissue sarcoma as well as head and neck squamous cell carcinoma, which is in accordance with the present study." (PMID 29270239, 2017).
chronic kidney disease (1 paper, 2023). Impairment of the renal function secondary to chronic kidney damage persisting for three or more months. "The role of STK3 in the inflammatory response has been discussed in the setting of septic arthritis, chronic kidney disease, and sepsis-induced phagocyte activation." (PMID 37056939, 2023).
cyst (1 paper, 2021). A sac-like closed membranous structure that may be empty or contain fluid or amorphous material. "Hematoxylin and Eosin (H&E) staining revealed that Wwtr1 OE larvae exhibited renal tubule dilation and glomerular cyst formation with enlarged Bowman's space, which were nearly identical to the phenotypes of stk3−/− mutants." (PMID 34545930, 2021).
Dyspareunia (1 paper, 2023). Recurrent or persistent genital pain associated with sexual intercourse. "Moreover, we identified that regulation of DNAm at cg24360069, in STK3 on 8q22, was associated with a greater extent of endometriotic pelvic disease, presence of dyspareunia, and had an mQTL in high LD with the lead GWAS variant at this locus." (PMID 37587191, 2023).
Intellectual disability (1 paper, 2021). "In addition to this potential relationship with structural alterations, one of the female-specific DMRs was located in Stk3, a gene previously associated with intellectual disability." (PMID 34828381, 2021).
liver cirrhosis (1 paper, 2024). "In this setting, CCl4 was administered for 12 weeks after the tail vein injection of Cre-expressing adenovirus (adeno-Cre) in Stk4(−/−)Stk3(F/−) (also known as Mst1(−/−)Mst2(F/−); F indicates a floxed allele) mice, and it resulted in the development of HCC tumors concomitantly with liver cirrhosis." (PMID 39062197, 2024).
medulloblastoma (1 paper, 2025). A malignant, invasive embryonal neoplasm arising from the cerebellum. "ElasticNet coefficients highlighted the predictive importance of genes such as AXIN1, RNF43, STK3, LEF1, and DKK1 for identifying the WNT subtype status in this medulloblastoma validation cohort." (PMID 39851951, 2025).
Moyamoya disease (1 paper, 2024). Moyamoya disease (MMD) is a rare intracranial arteriopathy involving progressive stenosis of the cerebral vasculature located at the base of the brain causing transient ischemic attacks or strokes. "Therefore, we can infer that in moyamoya disease, STK3 will promote the proliferation of VSMCs through the KRAS signaling pathway, HEDGEHOG signaling pathway and others in a similar way." (PMID 38704490, 2024). "Next, the expression levels of five key genes were found to correlate with the expression levels of several moyamoya disease-related genes, with H19 positively correlating with ADARB2 (Pearson r = 0.628) and STK3 negatively correlating with ISG15 (Pearson r = − 0.556)." (PMID 38704490, 2024).
ovarian endometriosis (1 paper, 2025). A non-neoplastic disorder characterized by the growth of endometrial tissue in the ovaries. "In ovarian endometriosis, it has been shown that CDKN2B antisense RNA 1 (CDKN2B-AS1) regulates AKT serine/threonine kinase 3 (AKT3) expression by sponging miR- 424-5p." (PMID 40792071, 2025).
Parkinson disease (1 paper, 2020). A progressive degenerative disorder of the central nervous system characterized by loss of dopamine producing neurons in the substantia nigra and the presence of Lewy bodies in the substantia nigra and locus coeruleus. "In a study of dominant mutation of LRRK2 (leucine-rich repeat kinase 2) in a Parkinson’s disease (PD) model, TAOK3, serine/threonine kinase 3 (STK3), STK24, and STK25 were identified to be novel LRRK2 substrates that may be involved in LRRK2-induced synaptic dysfunction and neurite fragmentation." (PMID 33050415, 2020).
prostate adenocarcinoma (1 paper, 2021). "The STK3 mutation rate is very low in prostate adenocarcinoma samples deposited in CBioportal, whilst 70 CRPC samples did not present any mutations." (PMID 33557087, 2021). "However, 7.3% of prostate adenocarcinomas had amplification of STK3." (PMID 33557087, 2021).
prostate tumors (1 paper, 2015). "Low levels of STK3 were detected in less aggressive prostate tumors using TCGA dataset." (PMID 25707771, 2015).
Renal cyst (1 paper, 2021). A fluid filled sac in the kidney. "Overall, our analyses revealed roles of Stk3 and Wwtr1 in renal cyst formation." (PMID 34545930, 2021).
Sepsis (1 paper, 2023). Sepsis is defined as life-threatening organ dysfunction caused by a dysregulated host response to infection. "Therefore, we performed both ultrastructural analysis and molecular assays to evaluate whether STK3 expression contributes to sepsis-related myocardial injury through disruption of mitochondrial homeostasis." (PMID 37056939, 2023). "Our results showed that sepsis does not alter cardiac KEAP1 expression, but induces instead its phosphorylation at T85 through upregulation of STK3." (PMID 37056939, 2023).
serous ovarian cancer (1 paper, 2020). "Our results revealed a new molecular mechanism for serous ovarian cancer malignancy mediated by STK3 through regulating NF-κB signaling and CD8+ T-cell recruitment." (PMID 33062724, 2020). "We also used a wound healing assay to determine the effect of STK3 on the migration of serous ovarian cancer cells OVCAR3 and OVCAR8." (PMID 33062724, 2020). "The results showed that the migration ability of serous ovarian cancer cells was significantly decreased in the STK3 overexpression group compared with the control group (P value <0.05)." (PMID 33062724, 2020).
Stroke (1 paper, 2024). Sudden impairment of blood flow to a part of the brain due to occlusion or rupture of an artery to the brain. "STK3 inhibitors improved metabolic patterns in obese mouse models, suggesting that there may be a viable pathway to investigate and develop drugs targeting STK3 to treat obesity-related diseases including stroke." (PMID 38650649, 2024).
Virus Infection (1 paper, 2017). "Our data expand the role of STK3 during viral infection, provide new information regarding the host cell kinases that are involved in viral replication, and identify potential targets for future antiviral strategies." (PMID 29226127, 2017). "In veterinary research, the roles of STK3 in bacterial or viral infections have not been reported." (PMID 29226127, 2017).
tumor (56 papers, 2011 to 2025). "We also found that upregulation of p-STK3/4 is associated with increased inhibition of tumor progression." (PMID 38436783, 2024). "STK3 encodes Serine/threonine-protein kinase 3, which is part of the Hippo pathway that plays an important role in tumor suppression by reducing cellular growth and promoting apoptosis." (PMID 37587191, 2023). "STK3 (also known as MST2) encodes serine/threonine-protein kinase 3, a component of the Hippo pathway that plays an important role in organ size regulation and tumor suppression by restricting proliferation and promoting apoptosis." (PMID 28934986, 2017). "Further analysis of the TCGA-STAD cohort demonstrated a similar pattern of STK3, which indicates a strong oncogenic potential of this traditionally recognized tumor suppressor gene." (PMID 40604818, 2025). "Serine/threonine kinase 3 (STK3) is recognized as a key regulator in Hippo pathway and a tumor-suppressing gene in various cancer types." (PMID 40604818, 2025). "Hippo signaling is suppressed in alveolar RMS cell lines and tumors, and genetically inhibiting the Hippo/MST signaling by knocking out kinases MST1 and MST2 (Stk4, Stk3), led to more rapid Pax3::Foxo1 tumor onset and higher penetrance." (PMID 40599857, 2025). "STK3 is a key enzymatic component within the Hippo signalling pathway (Figure A2A) that is vital for controlling tumour suppression via the restriction of cellular proliferation and the promotion of apoptosis." (PMID 40566602, 2025). "High throughput virtual screening was performed on an anti-tumor chemical library to identify novel inhibitors of STK3." (PMID 40604818, 2025). "The canonical tumor suppressor function of STK3 was considered to be largely dependent on regulating the phosphorylation and then degradation of active YAP1." (PMID 40604818, 2025). "Given its promoting function in the YAP1 phosphorylation and degradation process, STK3 is canonically considered as a tumor suppressor gene." (PMID 40604818, 2025). "Consistently with the organoid assay results, knocking down of STK3 significantly increased the anti-tumor efficiency of 5-FU, which was represented by the largely limited xenograft formation in mice of co-administration group." (PMID 40604818, 2025). "Our research underscores the anti-tumor function of STK3 in ESCC and elucidates the mechanism underlying its anti-tumor effect on ESCC." (PMID 38436783, 2024). "The results demonstrated that the deletion of STK3 expression substantially promotes tumor progression and augments tumor size." (PMID 38436783, 2024). "In conclusion, our study first demonstrated the potential tumor-suppressive role and the relative mechanism of STK3 in ESCC." (PMID 38436783, 2024). "Our studies provide further evidence that contradicts the previously accepted role of STK3 as a universal tumor suppressor and that in some cancers it has a tumor supportive role." (PMID 37345153, 2023). "We previously showed that contrary to its accepted role as a tumor suppressor, the STK3 gene is amplified in several cancer types and correlates with worse outcomes." (PMID 37345153, 2023). "By knowing that MST1/STK4 mainly functions as a tumor suppressor, while MST2/STK3 can act as an oncogene, the role of MST3/STK24 in carcinogenesis should be determined." (PMID 37181807, 2023). "STK3 (also known as MST2) is a key member of the Hippo Tumor-Suppressor Pathway, which regulates cell growth and proliferation by inhibiting YAP/TAZ co-transcription factors." (PMID 37345153, 2023). "In vitro cell proliferation, apoptosis, and migration assays, and in vivo subcutaneous xenograft tumor models were used to determine the roles of STK3." (PMID 33062724, 2020). "The results showed that the tumor volume and tumor weight of the lentivector group were larger than those of the lenti-STK3 group." (PMID 33062724, 2020).